TTLL3 (tubulin tyrosine ligase like 3)
Description:
Monoglycylase which modifies alpha- and beta-tubulin, adding a single glycine on the gamma-carboxyl groups of specific glutamate residues to generate monoglycine side chains within the C-terminal tail of tubulin. Not involved in elongation step of the polyglycylation reaction (By similarity). Preferentially glycylates a beta-tail peptide over the alpha-tail, although shifts its preference toward alpha-tail as beta-tail glutamylation increases (By similarity). Competes with polyglutamylases for modification site on beta-tubulin substrate, thereby creating an anticorrelation between glycylation and glutamylation reactions (By similarity). Together with TTLL8, mediates microtubule glycylation of primary and motile cilia, which is essential for their stability and maintenance (By similarity). Involved in microtubule glycylation of primary cilia in colon which controls cell proliferation of epithelial cells and plays an essential role in colon cancer development. Together with TTLL8, glycylates sperm flagella which regulates axonemal dynein motor activity, thereby controlling flagellar beat, directional sperm swimming and male fertility (By similarity).
Synonyms: DKFZP434B103; HOTTL
Tractability: PROTAC: ubiquitination databases record sites on it.
Gene: Protein-coding gene on chromosome 3 (9,808,086 to 9,855,138, forward strand). Ensembl gene ENSG00000214021.
Subcellular location: Cytoplasm, cytoskeleton; Cell projection, cilium; Cytoplasm, cytoskeleton, cilium axoneme; Cytoplasm, cytoskeleton, flagellum axoneme
Pathways (Reactome):
Metabolism of proteins: Carboxyterminal post-translational modifications of tubulin
Gene Ontology:
Molecular function: protein-glycine ligase activity; protein-glycine ligase activity, initiating
Biological process: protein polyglycylation; axoneme assembly; cilium assembly; flagellated sperm motility; spermatogenesis
Cellular component: axoneme; cilium; cytosol; microtubule cytoskeleton; sperm flagellum; cytoskeleton
Genetic constraint (gnomAD): Loss-of-function variants: 63 observed, 73.82 expected, observed/expected ratio (o/e) 0.85, 90% interval 0.7 to 1.05. The upper end of that interval is the gene's LOEUF score, 1.05, which puts it in group 4 of 6, group 1 being the genes least tolerant of losing a copy. Missense variants: 990 observed, 1,080.1 expected, observed/expected ratio (o/e) 0.92, 90% interval 0.87 to 0.97. Synonymous variants: 391 observed, 421.94 expected, observed/expected ratio (o/e) 0.93, 90% interval 0.85 to 1.01.
Homologues: Orthologues: chimpanzee TTLL3 (93% identical), macaque TTLL3 (92% identical), pig TTLL3 (74% identical), mouse Ttll3 (71% identical), rat Ttll3 (71% identical), dog TTLL3 (70% identical), rabbit TTLL3 (60% identical), tropical clawed frog XB5950141 (47% identical), zebrafish ttll3 (40% identical), tropical clawed frog ttll3 (38% identical). Paralogues in human: TTLL8 (35% identical), TTLL6 (14% identical), TTLL13 (13% identical), TTLL4 (13% identical), TTLL1 (13% identical), TTLL7 (13% identical), TTLL10 (12% identical), TTLL9 (12% identical), TTLL2 (11% identical), TTLL11 (11% identical), TTLL12 (10% identical), KPRP (7% identical).
Diseases named in the same sentence as TTLL3 in open-access papers:
TTLL3 is named in the same sentence as 12 diseases in open-access papers, as found by Europe PMC text mining. Sharing a sentence is not in itself a finding about the gene and the disease. The quoted sentences say what the papers report.
colorectal cancer (2 papers, 2025). A primary or metastatic malignant neoplasm that affects the colon or rectum. "Loss of the glycylase TTLL3 leads to a reduction in primary cilia and increased rates of cell division in colon epithelial cells, and TTLL3-inactivating mutations were identified in patients with colorectal cancer." (PMID 40799597, 2025). "Studies have shown that TTLL3 is expressed in colon tissues, and its absence or decreased levels of its expression lead to the deficiency of tubulin glycosylation and a reduction in primary cilia, thereby promoting the development of colorectal cancer." (PMID 41019085, 2025).
colon cancer (1 paper, 2020). "Accordingly, the experimental loss of TTLL3 in a mouse model of tumorigenesis resulted in the development of cancer, thus validating its downregulation in colon cancer and suggesting a cancer-suppressing role for tubulin glycylation." (PMID 33114575, 2020). "In this regard, the tubulin glycylase TTLL3 was proposed to restrict cell proliferation in the colon and is downregulated in colon cancer, whereas the tubulin glutamylase TTLL4 was suggested to promote cell proliferation in pancreatic cancer cells." (PMID 33114575, 2020).
lymphoma (1 paper, 2023). A malignant (clonal) proliferation of B- lymphocytes or T- lymphocytes which involves the lymph nodes, bone marrow and/or extranodal sites. "However, the exact roles and specific functions of FHIP2B, POMT1, TTLL3, CROCC, and CD52 in lymphoma and the molecular mechanisms of their downmodulation upon MyD88L265P expression are not yet fully understood and require further research." (PMID 36982699, 2023).
retinal degeneration (1 paper, 2022). Degeneration of the retina. "With the emerging role of enzymes involved in tubulin glycylation and glutamylation in retinal degeneration, the clinical and cellular phenotype associated with PRPF6 and PRPF31 mutations, TTLL3 is an extremely interesting candidate for further investigation." (PMID 36176300, 2022). "Ttll3−/− mice lack glycylation in photoreceptors, which results in shortening of connecting cilia and slow retinal degeneration." (PMID 36176300, 2022). "We identify that TTLL3 is the only tubulin glycylase expressed in the human retina, essential for monoglycylation of microtubules of the cilium, including the retinal photoreceptor cilium, to prevent cilium degeneration and retinal degeneration." (PMID 36176300, 2022).
TTLL3 also shares sentences with these, for which no sentence is quoted: cancer (5 papers); Fanconi anemia (1); gastric cancer (1); lung carcinoma (1); metabolic disorders (1); neurological diseases (1); osteoarthritis (1); theileriasis (1).